SWAP70 (switching B cell complex subunit SWAP70)
Diseases named in the same sentence as SWAP70 in open-access papers (continued):
Sharing a sentence is not in itself a finding about the gene and the disease.
tumor (continued). "It has been suggested that SWAP-70 is important for cell motility and invasion of the tumor cells." (PMID 21152038, 2010). "In addition, SWAP-70 most likely through actin-dependent control of receptor function supports cell adhesion and thus another process that is instrumental for metastatic tumor cells to reach and home into target organs." (PMID 38760173, 2024). "To assess whether SWAP-70 is specifically required for the initiation of metastasis or is necessary at subsequent steps as well, we undertook tail vein injections of tumor cells to bypass the initial steps of dissociation from the primary tumor and entry into blood vessels." (PMID 38760173, 2024). "Because changes in cytoskeletal dynamics in tumor cells can correlate with the EMT, which can be triggered by TGFβ/EGF used in the cellular assays in our report, we analyzed the requirement for SWAP-70 for the expression of EMT markers by several approaches." (PMID 38760173, 2024). "Inoculation of MEFs into nude mice showed that tumor volumes from MEFs lacking SWAP-70 were significantly smaller than those from MEFs expressing exogenous SWAP-70." (PMID 31832018, 2019). "Five of the GEFs described to promote GB cell motility, including Ect2, Vav3, Trio, SGEF, and SWAP-70, are overexpressed in GB versus non-neoplastic brain, and Dock180 expression is higher in the tumor rim than in the tumor core." (PMID 24109588, 2013). "However, neither studies on the role of SWAP-70 in tumor metastasis in vivo were reported, nor were potential mechanisms described." (PMID 38760173, 2024). "It has only been reported that SWAP-70 is involved in phosphoinositide-3-kinase (PI3K) downstream signaling and activation of Rac, which subsequently regulates cytoskeletal changes that affect membranous cellular fold formation, thereby regulating tumor cell migration and invasion." (PMID 31832018, 2019).
cancer (8 papers, 2010 to 2024). A tumor composed of atypical neoplastic, often pleomorphic cells that invade other tissues. "Switch-associated protein 70 (SWAP-70) is a guanine nucleotide exchange factor that is involved in cytoskeletal rearrangement and regulation of migration and invasion of malignant tumors." (PMID 31832018, 2019). "In this study, we found that SWAP-70 mutations found in human cancer can transform mouse NIH3T3 cells." (PMID 23555004, 2013). "SWAP-70 also plays an important role in the oncogenesis of GB, prostate cancer, and other malignant tumors." (PMID 31832018, 2019). "In this paper, we demonstrate that a mutant of SWAP-70 can transform mouse embryo fibroblast and further suggest that an anti-cancer drug, sanguinarine inhibits SWAP-70-dependent cell responses." (PMID 21152038, 2010). "Although clinical cancer databases do not present SWAP-70 as a major cancer-associated factor, SWAP-70 was experimentally implicated in a few cancer-related settings." (PMID 38760173, 2024). "SWAP-70 expression in malignant tumors is higher than that in normal tissues, indicating that it may be closely related to oncogenesis in vivo." (PMID 31832018, 2019). "Studies have shown that SWAP70 is involved in signaling B cell activation and may have a potential oncogenic function in cancer." (PMID 27738332, 2016). "Although how SWAP-70 contributes to the formation of cancers is largely unknown, some of SWAP-70's activities at the biochemical or cell biological level have been revealed." (PMID 21152038, 2010). "It has been shown that SWAP-70 is closely related to malignancy of cancer." (PMID 21152038, 2010). "In these specific intergroup DE genes, BCL11A, VPREB3, CD79B, CHRNA7, and SWAP70 that all involved in B cell proliferation and activation, would likely impact B cell function in MDV pathogenesis and malignant tumor formation." (PMID 30922224, 2019).
cardiovascular disease (1 paper, 2022). "Six genes (TKT, TCF4, SWAP70, DDHD2, ARHGAP31, and LTB) showed significant associations of genetic variants with the risk of cardiovascular disease." (PMID 36204511, 2022).
SWAP70 also shares sentences with these, for which no sentence is quoted: B-cell neoplasm (1 paper); bone disorder (1); colorectal cancer (1); experimental autoimmune encephalomyelitis (1); Hepatic steatosis (1); Hypertension (1); metastatic tumor (1); nonalcoholic fatty liver disease (1); osteoarthritis (1); ovarian carcinoma (1); pancreatic adenocarcinoma (1); triple-negative breast carcinoma (1); type 2 diabetes (1).